SQSTM1 (sequestosome 1)
Diseases named in the same sentence as SQSTM1 in open-access papers (continued):
Sharing a sentence is not in itself a finding about the gene and the disease.
Nasu-Hakola disease (1 paper, 2020). "In patients diagnosed with AD we found three C9orf72 expansions, nine DVs in MAPT, five in CSF1R, two in GRN, three in PRNP and one each in SQSTM1, TARDBP and VCP, as well as a homozygous TREM2 DV normally associated with Nasu-Hakola disease." (PMID 30279455, 2020).
nephrolithiasis (1 paper, 2021). The presence of a calculus in the pelvis of the kidney; this is most often composed of mineral salts and proteins. "Genes in this crosstalk include those previously reported to be of functional relevance to nephrolithiasis, such as protein kinase C (PRKCA, PRKCB, and PRKCZ), markers (CD40 and TLR3), and autophagy (MTOR and SQSTM1), thus validating our genetic prioritization at the gene and pathway level." (PMID 34489936, 2021).
neurofibromatosis type 1 (1 paper, 2015). A clinically heterogeneous, neurocutaneous genetic disorder characterized by cafe-au-lait spots, iris Lisch nodules, axillary and inguinal freckling, and multiple neurofibromas. "Thus, our results suggest that, like in neurofibromatosis type 1, pagetic patient carriers of a SQSTM1/P392L post-zygotic mutation would develop a less extensive bone involvement than patients harboring the germ line mutation." (PMID 25241215, 2015).
pancreatic insulinoma (1 paper, 2023). An insulin-producing neuroendocrine tumor arising from the beta cells of the pancreas. "In particular, pancreatic insulinomas (n = 24) showed a higher expression of the autophagic genes BECN1 (p < 0.001), MAP1LC3B (p < 0.001), SQSTM1 (p = 0.008), TFEB (p < 0.001), PRKAA1 (p = 0.038), and PRKAA2 (p = 0.019) compared to NF-pNET (n = 7)." (PMID 36835048, 2023).
parathyroid adenoma (1 paper, 2024). "SQSTM1 fusion was associated with multifocality and a medical history of thyroid/parathyroid adenoma." (PMID 39409115, 2024). "SQSTM1 fusion also clustered well with multifocality and with a medical history of thyroid/parathyroid adenoma." (PMID 39409115, 2024).
pericardial effusion (1 paper, 2024). Fluid collection within the pericardial sac, usually due to inflammation. "We have, for the first time, identified the presence of SQSTM1-ALK fusion in pericardial effusion, with the favorable response to ensartinib validating the oncogenic potential of SQSTM1-ALK fusion." (PMID 39555099, 2024).
prediabetes (1 paper, 2024). "An increased LC3-II/LC3-I ratio was also observed in liver samples from MASLD patients with prediabetes, nonetheless, the level of p62/SQSTM1 protein was not affected in the studied cohort, which complicates the interpretation of these results." (PMID 38971910, 2024).
Premature ovarian insufficiency (1 paper, 2022). Amenorrhea due to loss of ovarian function before the age of 40. "Moreover, the downregulation of autophagy was also apparent in premature ovarian insufficiency patients, as evidenced by the lower LC3 and higher SQSTM1/p62 gene, which prevented GCs differentiation." (PMID 36359843, 2022).
primary progressive aphasia (1 paper, 2025). Primary progressive aphasia (PPA) is a neurodegenerative disorder, characterized by a primary dissolution of language, with relative sparing of other mental faculties for at least the first 2 years of illness. "One study reported the co-occurrence of CHCHD10 and C9orf72 variants in an ALS-FTD patient, and another reported a person carrying both TBK1 and SQSTM1 variants, who was diagnosed with non-fluent variant primary progressive aphasia (nfv-PPA)." (PMID 40170896, 2025).
Progressive cerebellar ataxia (1 paper, 2022). "Some variants of SQSTM1 gene are common to both PDB and ALS/FTD, others have been suggested to be ALS/FTD specific, and in rare cases like the presented case, the mutation was reported linked to childhood‐onset progressive cerebellar ataxia with vertical gaze palsy." (PMID 35957775, 2022).
proliferative diabetic retinopathy (1 paper, 2025). Advanced retinopathy due to diabetes mellitus characterized by the formation of new vessels in the retina. "Single-cell RNA-Seq of human proliferative diabetic retinopathy (PDR) retinas confirmed elevated SQSTM1 expression in Müller cells compared to healthy control (HC) retinas." (PMID 40843317, 2025).
pterygium (1 paper, 2025). A wedge-shaped fibrovascular lesion arising from the bulbar conjunctiva and extending to the cornea. "The current research suggests that autophagic dysfunction promotes fibrosis and pterygium occurrence by activating the SQSTM1–PKCι–NF-κB signaling pathway." (PMID 40238115, 2025). "In the context of pterygium, autophagy exerted inhibitory effects on the SQSTM1–NF-κB signaling pathway through the degradation of the SQSTM1 protein, thereby exerting negative regulation on fibroblast fibrosis and subsequently impacting the progression of pterygium." (PMID 40238115, 2025).
pulmonary tuberculosis (1 paper, 2024). A bacterial infection that affects the lungs and is caused by Mycobacterium tuberculosis. "Upregulated SQSTM1/p62 promotes the secretion of inflammatory mediators by activating the NF-κB signaling pathway, which in turn reduces macrophage apoptosis and promotes the survival of Mtb in macrophages, ultimately leading to the occurrence and progression of pulmonary tuberculosis." (PMID 38433218, 2024).
rhabdomyosarcoma (1 paper, 2022). A rare aggressive malignant mesenchymal neoplasm arising from skeletal muscle. "Furthermore, in vitro and in vivo passive immunization models with immunoglobulin G extracted from anti-cN1A–seropositive IBM patient serum samples have been found to exhibit higher p62/SQSTM1 expression and abundant aggregations in the cytoplasm of supplemented rhabdomyosarcoma cells." (PMID 36189221, 2022).
sarcopenia (1 paper, 2018). Progressive decline in muscle mass due to aging which results in decreased functional capacity of muscles. "The aggregation of ubiquitin and p62/SQSTM1 proteins has also been observed in skeletal muscle of the patients with myopathy- or autophagy-specific gene knockout rats and the mice with sarcopenia." (PMID 29849885, 2018).
SARS-CoV infections (1 paper, 2022). "In the present study, a sum of three polymorphisms (SQSTM1 rs10277, IL1B rs1143627, EGFR rs712829) of 2-DG interacting genes may increase the susceptibility to SARS-CoV infections than other polymorphisms." (PMID 36164436, 2022).
serous ovarian cancer (1 paper, 2022). "The abnormal amplification and phosphorylation of p62/SQSTM1 has been linked to tumor growth and cisplatin resistance in patient-derived high-grade serous ovarian cancer cells." (PMID 35326612, 2022).
skin tumors (1 paper, 2023). "It was verified that UVA- induced SQSTM1 could act through COX-2 to promote the growth and progression of skin tumors." (PMID 38099574, 2023).
small cell lung carcinoma (1 paper, 2025). Small cell lung cancer (SCLC) is a highly aggressive malignant neoplasm, accounting for 10-15% of lung cancer cases, characterized byrapid growth, and early metastasis. "SQSTM1 showed enrichment in small cell lung cancer (ES = 0.598, NES = 1.50, p = 0.0021), phosphatidylinositol signaling system (ES = 0.607, NES = 1.39, p = 0.0139), mTOR signaling pathway (ES = 0.617, NES = 1.37, p = 0.0172), among others." (PMID 41105646, 2025).
Takotsubo cardiomyopathy (1 paper, 2023). "Of interest, genetic variants in BAG cochaperone 3 (BAG3), which has an important role in autophagy through binding to SQSTM1, have been associated with Takotsubo cardiomyopathy." (PMID 37569694, 2023).
testicular cancer (1 paper, 2024). A primary or metastatic malignant neoplasm that affects the testis. "In a panel of human cell lines derived from breast, colorectal, head and neck, and testicular cancers, we demonstrated that PV-10 induces cytotoxicity by apoptotic and autophagic pathways involving caspase-mediated PARP cleavage, downregulation of SQSTM1/p62, and upregulation of beclin-1." (PMID 38672602, 2024).
type 1 diabetes (1 paper, 2022). "Their conclusion of increased autophagy was partially based on findings of increased LC3-II and p62/sequestosome-1 level in a type 1 diabetes model." (PMID 35846001, 2022).
uveal melanoma (1 paper, 2022). A melanoma derived from melanocytes of the uveal tract. "The risk score for the uveal melanoma TCGA cohort was calculated as follows: risk score = (0.8578 × SQSTM1 expression) + (−1.2004 × ATG9A expression) + (−2.0815 × GABARAPL1 expression)." (PMID 36292980, 2022).
vacuolar myopathy (1 paper, 2022). "Based on the pathophysiological similarities (especially regarding p62/SQSTM1), protein dysregulations common in sIBM and VCP–related myopathy have also been studied by investigating muscle tissue derived from Vcp–mutant mice presenting with a vacuolar myopathy." (PMID 36289705, 2022).
vascular tumor (1 paper, 2018). "For SQSTM1, it showed different expression in terms of age, gender and vascular tumor cell type." (PMID 29707114, 2018).
ZIKV infection (1 paper, 2018). "A decrease in p62/SQSTM1 levels with ZIKV infection was reported in fNSCs, indicating that autophagy maturation and lysosomal fusion were most likely not impaired." (PMID 30374352, 2018).
tumor (191 papers, 2010 to 2026). "Autophagy deficiency in apoptosis-defective tumor cells leads to the accumulation of SQSTM1, which subsequently provokes a positive feedback cycle of ROS generation and further genomic instability and tumorigenesis." (PMID 39941813, 2025). "From an initial set of 76 patients diagnosed with PTC, we utilized qRT-PCR to assess the expression levels of four characteristic genes associated with OSPTCC subtypes (APOE, APOC1, DEPTOR, and SQSTM1) in patient tumor samples." (PMID 40650680, 2025). "Tumor development has been linked to SQSTM1 gene amplification as well as abnormal SQSTM1 accumulation and phosphorylation." (PMID 39463763, 2024). "In the TME, SQSTM1 regulates the function of tumor-associated macrophages, affects immune escape and inflammatory responses in tumors, and promotes malignant invasion and metastasis by regulating extracellular matrix (ECM) degradation." (PMID 39600313, 2024). "Protein p62 (sequestosome 1) encoded by gene SQSTM1 plays a vital role in mediating protectively selective autophagy in tumor cells under stressed conditions." (PMID 36650519, 2023). "SQSTM1 was upregulated and associated with poor prognosis as well as regulated the occurrence and development of tumor through various mechanisms." (PMID 36157211, 2022). "The genetic loss of Atg5 and Atg7 increased the levels of SQSTM1/p62, oxidative stress, mitochondrial swelling, and genomic damage observed in the primary hepatocytes, and the deletion of the p62 gene reduced the tumor size in Atg7 deficient hepatic tumors." (PMID 35252196, 2022). "Paradoxically, it has been seen that the upregulation of p62/SQSTM1 is associated with human tumour progression and downregulation induces cancer progression in cancer-associated fibroblasts." (PMID 33802014, 2021). "In basal breast cancer, the archetypal Wnt/PCP protein VANGL PCP protein 2 (VANGL2) is upregulated and is associated with poor prognosis and tumour growth through the VANGL2‐p62/SQSTM1‐JNK pathway." (PMID 32391621, 2020). "Elevated SQSTM1 is considered a hallmark for impaired autophagy and has been associated with poor prognosis in some tumor types." (PMID 28749466, 2017). "Elevation of SQSTM1 is considered as a hallmark for impaired autophagy and has been associated with poor prognosis in some tumor types." (PMID 26775697, 2016). "They find that Pep2‐A2 displays a significant inhibition of SQSTM1/TRIB3 interaction in tumor cells, rescuing the TRIB3‐reduced association of SQSTM1 with LC3 and ubiquitinated proteins." (PMID 27038142, 2016). "In addition, it has been shown that phosphorylation of SQSTM1 is closely associated with cisplatin resistance in tumor cells and the progression of the TAR DNA binding protein (TARDBP) associated neurodegenerative diseases." (PMID 39621600, 2024). "Moreover, various proteins associated with autophagy that directly suppress tumour development include Beclin-1, UVRAG, and Bif-1, as well as components that destroy proteins associated with tumour growth such as p62/SQSTM1." (PMID 34445354, 2021). "A clear accumulation of SQSTM1 and UB in the tumor region of the autophagy-deficient liver was observed, which was at the level similar to that in the non-tumor tissues, suggesting that the tumor tissues were defective in autophagy and had defective protein quality control." (PMID 32382012, 2020). "Similar to FXR, the association of p62/SQSTM1 with tumor have been reported." (PMID 28086800, 2017). "In cancer, the expression level of SQSTM1/P62 is often correlated with tumor progression and prognosis." (PMID 41436732, 2025). "Mice with liver-specific Atg7 knockout develop liver tumors, while knockout of SQSTM1/p62 reduces tumor size." (PMID 40229278, 2025). "The increase in P62/SQSTM1 levels and the upregulation of NF-κB contribute to immune evasion and the increased infiltration of tumor lymphocytes, which can be attributed to the inhibition of autophagy." (PMID 40723786, 2025).
tumor (continued). "The protein expression patterns of LC3-II/LC3-I and SQSTM1 (p62) in tumor tissues from itraconazole-treated mice mirrored the in vitro findings." (PMID 39917616, 2025). "CRCs expressing SQSTM1/P62 have been reported to modulate immunosuppressive Foxp3 regulatory T cells inside the tumor microenvironment." (PMID 40066091, 2025). "Certain factors upregulated in tumor cells, like p62/SQSTM1, play key roles in autophagy, inflammation, and/or oxidative stress response to prevent cell death." (PMID 40361329, 2025). "SQSTM1 regulates metabolism through autophagy to provide nutrients that favor the survival and proliferation of tumor cells." (PMID 39744571, 2025). "In OSCC, SQSTM1/P62 mRNA expression was significantly upregulated in tumor tissues compared with their matched adjacent normal controls." (PMID 41436732, 2025). "This blockade results in the accumulation of SQSTM1/p62 which promotes tumour survival under cisplatin-induced stress." (PMID 40805271, 2025). "The association of a high expression of SQSTM1 with poor prognosis is further supported by findings that have demonstrated its involvement in oncogenic signaling pathways through the activation of mTORC1, which may shift cellular metabolism toward anabolism—an advantageous state for tumor cells." (PMID 39941813, 2025). "During the process of autophagy, SQSTM1/p62 can be specifically degraded after action, while defective autophagy leads to the accumulation of SQSTM1/p62, which damages mitochondria and DNA, increases oxidative stress, and further promotes tumor cell growth." (PMID 40231206, 2025). "BAFF released from monocyte-derived nurse-like cells (NLCs) present in the tumor microenvironment enhances the accumulation of p62/SQSTM1, which triggers Nrf2 activation in CLL cells." (PMID 40422216, 2025). "Ras-driven transformation enhances SQSTM1 accumulation, which in turn increases NF-κB activity, dampening ROS production and inhibiting tumor cell death." (PMID 39941813, 2025). "SQSTM1, also known as p62, is a multifunctional signal adapter protein involved in both autophagy and apoptosis pathways in tumor cells." (PMID 38883131, 2024). "Autophagy cargo receptors, exemplified by Sequestosome 1 (p62), play multifaceted roles in cancer, and their maintenance through autophagy-mediated degradation is identified as a key tumor-suppressive mechanism." (PMID 38612567, 2024). "First, autophagy can function as a tumor suppressor during the initiation stage of hepatoneogenesis by reducing inflammation, SQSTM1 accumulation, the oxidative stress response, and ultimately genomic instability and through autophagic cell death." (PMID 39463763, 2024). "The overexpression of DDX5 in Huh7 xenografts not only suppressed tumor growth following sorafenib treatment but also repressed the protein level of p62/SQSTM1, a positive upstream effector of NRF2 stability." (PMID 39122708, 2024). "It has also been shown that HCV activates Nrf2 and that HCCs with the virus present (HCV-positive HCC, or C-HCC) have enhanced p62/Sqstm1 pathways, which promotes metabolic reprogramming and tumor growth in a manner that is reliant on Nrf2." (PMID 37946175, 2023). "Although the role of SQSTM1/p62 in solid tumors is still debated, evidence has shown that SQSTM1/p62 is upregulated in different cancers and promotes tumor growth." (PMID 37373349, 2023). "Similar to in vitro experiments, birinapant elevated the LC3‐II level, accompanied by the down‐regulation of SQSTM1/p62 in tumour tissues in the birinapant treatment group, indicating that autophagy does occur in the birinapant‐treated AML cells." (PMID 37154878, 2023). "Particularly, increased DNA damage, high ROS levels, aneuploidy, and an aberrant accumulation of p62/SQSTM1 have been correlated with an impaired autophagic process, indicating a key role of autophagy in preventing tumor initiation." (PMID 37296673, 2023).